CD4 (CD4 molecule)
Diseases named in the same sentence as CD4 in open-access papers (continued):
Sharing a sentence is not in itself a finding about the gene and the disease.
tumor (continued). "As CD4+ T helper cells have been shown to significantly contribute to boosting anti-tumor cytoxicity, a co-transfer of CD4+ and CD8+ T cells can be envisaged as being part of optimized ACT protocols." (PMID 27177227, 2016). "Taken together, these data suggested that the number of tumor-reactive CD4+ T cells at equilibrium was a major determinant of tumor control." (PMID 27121060, 2016). "Several reports have shown that CD4+ T-cells have efficacy in ACT either through supporting the direct cytotoxic function of CD8+ T-cells or via indirect CD4+ dependent mechanisms of tumor cell killing." (PMID 27657129, 2016). "Substantial or complete tumor regressions have been achieved by ACT of T cells consisting only or mainly of CD4+ T cells." (PMID 27619514, 2016). "The inclusion of GM-CSF in anti-tumor treatments increases levels of both CD4+ and CD8+ T cells and can stimulate potent, long-lasting, and specific immunity." (PMID 28191451, 2016). "To rule out the possibility that the reduced TH17 and TH1 cell differentiation was due to abnormal cell death caused by 5-FU, we analyzed CD4+ T cells from spleens as well as lymph nodes of C57BL/6 mice and tumor cell lines." (PMID 27027355, 2016). "Prophylactic vaccination with IL-21 and IL-7 co-expressing B16F10 cells and tumor challenge were repeated in wild-type, CD4 knockout and CD8 knockout (KO) mice in this study." (PMID 27571893, 2016). "Depletion of either CD8+ T cells or CD4+ T cells nearly eliminated the anti-tumor effect of the combinational treatment of MMC DRibbles and anti-OX40 antibody." (PMID 27874054, 2016). "Immune plasticity, and in particular that of CD4+ cells, further complicates conclusive determinations of the role of inflammation in tumor progression." (PMID 27453801, 2016). "The number of Foxp3+CD25+CD4+ cells is significantly lower within the tumor cell area as compared to the number outside the tumor cell area." (PMID 27999289, 2016). "We observed significantly higher tumor and splenic CD4+ T cell–derived IL17A production in the IL-10−/− B16/F10 mice but not in the TDLN (data not shown)." (PMID 27075020, 2016). "There was a significant association of T lymphocyte subsets (CD4+, CD8+, and FOXP3+) with tumour grade: infiltration by CD4+ and CD8+ T cells, intratumoural (p = 0.026 and p = 0.038, resp)." (PMID 27777963, 2016). "Negative correlations between the frequencies of IL-10-expressing B cells and the frequencies of granzyme A- and perforin-expressing CD4+ T cells were also observed in tumor-infiltrating cells." (PMID 27136203, 2016). "Carbon ions induce tumor death more effectively, which is beneficial to CD4+ T cell activation and proliferation." (PMID 27029063, 2016). "Multiple studies have demonstrated an enhanced anti-tumor effect when both CD4+ and CD8+ T cells were adoptively transferred, compared to CD8+ T cells alone." (PMID 27153556, 2016). "Surprisingly, CD4+ cells were at a low abundance in wild-type Py8119 tumours and further decreased 10 days after radiation." (PMID 28008921, 2016). "This is demonstrated in our recent work showing that autoimmune vitiligo is increased in tumor-bearing mice treated with CD4+ T cells specific for TRP-1 and antibodies to deplete NK1.1+ cells." (PMID 26981246, 2016). "In contrast, depletion of CD4+ T cells enhanced antitumor responses in tumor-bearing mice treated with control and therapeutic mAbs, likely due to the loss of intratumoral Tregs." (PMID 27610613, 2016). "CD4+ cells were scattered in high numbers all over the tissue both in and outside the tumor cell area." (PMID 27999289, 2016). "B cells also can promote anti-tumor immunity through providing Ags to both CD4+ and CD8+ T cells or through cross-presentation Ags to other APCs." (PMID 27331871, 2016). "Paclitaxel has also been shown to increase tumor infiltrating type 1 T-cells by increasing the expression of type 1 cytokines and decreasing Th2 CD4+ T-cells in the tumor." (PMID 27777769, 2016).
tumor (continued). "The expression of CD103 in lymphoid CD4+Foxp3+ cells was reported to recruit Tregs into tumor sites." (PMID 27036297, 2016). "We observed increased tumor infiltration following ipi by activated (CD69+) CD3+/CD4+ T cells (p = 0.06) and CD3+/CD8+ T cells (p = 0.2) compared to baseline." (PMID 27330811, 2016). "For example, high proportions of CD4+CD25+ T cells are present in the tumor-infiltrating lymphocytes (TILs) of patients with non-small cell lung cancer (NSCLC)." (PMID 28018902, 2016). "Tr1 cell generation from naïve CD4+ T cell precursors is promoted at tumor sites mainly through the action of immature DCs or tolerogenic pDCs, as shown by in vitro models of HNSCC, HCC and liver metastases of CRC." (PMID 27509527, 2016). "The frequency of tumor-infiltrating CD4+ T cells was higher in the CCR4 antagonist-treated group than in the control groups, but the difference was not statistically significant." (PMID 27177223, 2016). "Suppression by the tumor microenvironment is mediated by a unique subset of CD4+CD25highFoxp3+ Tregs that produce IL-10 and TGF-β, which lead to a more antiproliferative effects." (PMID 27044404, 2016). "Subsequently, MM patients can generate spontaneous immune responses to a wide range of these MM-specific antigens, via tumor-infiltrating lymphocytes (TILs), especially CD4- and CD8-positive T-lymphocytes." (PMID 27456492, 2016). "Our previous report with syngeneic tumor models indicated that GzmB is critical for the ability of CD4+CD25+ regulatory T (Treg) cells to suppress antitumor immune responses mediated by CD8+ cytotoxic T cells and natural killer (NK) cells." (PMID 27774524, 2016). "According to our data, the ratio of FOXP3+ vs CD4+ or CD8+ cells in both the tumor and stromal compartment had a prognostic value." (PMID 27463005, 2016). "Firstly, previous studies reported that the CD4/CD8 ratio was significantly lower in patients with higher tumor load and plasma concentration of Epstein-Barr virus DNA pre-treatment, indicating a higher risk of distant metastasis." (PMID 27270307, 2016). "The thymic tumor cells were clonal, showed either an immature phenotype with a CD4+CD8+ signature or were single-positive (SP) thymocytes." (PMID 27793024, 2016). "Antigen-presenting cells (APCs; namely DCs, macrophages and CD4+ T helper cells) endocytose the HSP-tumor peptide complex and present the chaperoned peptides directly to tumor-specific CTLs." (PMID 26807257, 2016). "Surprisingly and in contrast to the time directly after termination of CSC, splenic MO-MDSC from tumor-bearing CSC mice 9 days after termination of CSC were now more suppressive for CD4+ T cells (left) when compared to respective MO-MDSC from SHC mice." (PMID 27391954, 2016). "It has further been shown that B16 cells express MHC II in vivo, and can be directly recognized and eliminated by CD4+ T cells specific for the tumor-specific antigen Trp-1." (PMID 27626487, 2016). "CD4+ T cells exhibited elevated ICOS expression in the tumor/lungs of untreated controls and all treatment groups compared to naïve, tumor-free mice." (PMID 26961085, 2016). "In the presence of tumor-specific B cells, the number of tumor-reactive CD4+ T cells was reduced in lymphoid tissues and the tumor itself, and this correlated with poor tumor control." (PMID 27121060, 2016). "Only 1 of 26 mice with fewer than 6% circulating CD4+ T cells remained tumor free until sacrifice at day 120, compared with all 19 mice with more than 6% CD4+ T cells." (PMID 27121060, 2016). "Tumor and spleen-derived CD4+Foxp3+ Treg cells obtained from anti-TGF-β-treated IL-10−/− B16/F10 mice were significantly increased." (PMID 27075020, 2016). "In both studies vaccination with DC/MM fusions were well tolerated and stimulated tumor specific immunity as evidenced by expansion of tumor reactive CD4 and CD8 T cells and induction of tumor specific antibody responses." (PMID 26784207, 2016).
tumor (continued). "Our results indicate that both CD8+ and CD4+ T cells are required for the anti-tumor immunity induced by DRibble and anti-OX40 combination immunotherapy." (PMID 27874054, 2016). "Both TDLN and tumor-derived CD4+IFN-γ+ (Th1) cells were significantly elevated in IL-10−/− B16/F10 mice treated with the anti-Nrp-1 antibody." (PMID 27075020, 2016). "In response to CD4+ T cell help, B cells produced a range of isotype-switched anti-tumor antibodies, principally IgG1, IgG2a/c and IgG2b." (PMID 27121060, 2016). "There was a significant reduction in the proportion of regulatory T cells (CD25+FoxP3+) among CD4+ T cells, which are considered deleterious in cancer by suppressing active anti-tumor immunity." (PMID 27463016, 2016). "In several of these models, B cells inhibit T cell mediated tumor immunity and/or facilitate conversion of T cells to CD4+CD25+FoxP3+ T regs, which act to attenuate the innate and/or adaptive antitumor immune response." (PMID 27437104, 2016). "Idiotype-specific CD4+ Th1 cells can achieve tumor apoptosis directly by Fas/Fas L interaction and indirectly by IFN-γ production." (PMID 27428940, 2016). "The typical immunosuppressive tumour environment is characterised by a strong induction by CD4+, CD25+, FOXP3, and tumour-infiltrating regulatory T cells, and the activation of Th2 and Th17." (PMID 26913068, 2016). "These tumor-derived factors can dysfunctionalize antigen-presenting cells and enhance regulatory T cells, which suppresses intraturmoral CD4+ and CD8+ T lymphocytes." (PMID 27557492, 2016). "Additional investigation revealed that co-administration of LPS plus antibody depletion of host CD4+ T cells triggered robust tumor eradication." (PMID 26885368, 2016). "The proportion of CD57+ T cells, including both CD8+ and CD4+ subsets significantly increased with clinical stage, especially in parallel with tumor size as described by Iida and co-authors." (PMID 27044404, 2016). "Compared to that in peripheral blood, the level of IL-10-expressing B cells were further upregulated in resected tumor, while the level of CD4+ cytotoxic T cells was downregulated." (PMID 27136203, 2016). "Good clinical responses following ACT are related to recognition of tumor-specific antigens by both CD4+ and CD8+ T cells." (PMID 27619514, 2016). "On the other hand, CXCL10 raises proinflammatory IFN-γ expression that triggers CD4+ T lymphocytes release and promote tumor rejection." (PMID 27294132, 2016). "Several other studies have suggested that the immune response of tumor cells can be modulated by fludarabine, paclitaxel and cyclophosphamide, by decreasing or depleting CD4+CD25+Foxp3+ Tregs." (PMID 27389040, 2016). "Another report demonstrated that combining the most effective subsets of CD8+ and CD4+ CD19-expressing CAR-T cells resulted in a synergistic anti-tumor effect in vivo." (PMID 26999211, 2016). "Tumor-infiltrating FoxP3+CD25+CD4+ regulatory T (Treg) cells can promote local tumor growth through exerting immunosuppressive activities against tumor-associated antigen (TAA) T cell responses." (PMID 27177223, 2016). "In the current study, the presence of B cells reduced the numbers of tumor-reactive CD4+ T cells, which in turn correlated with a reduction in the effectiveness of long-term tumor control, defined as > 120 days tumor-free survival." (PMID 27121060, 2016). "Splenic CD4+Foxp3+ T cells and tumor CD4+Foxp3+ T cells obtained from IL-10−/− B16/F10 mice were significantly increased compared with WT mice." (PMID 27075020, 2016). "Combining MVA-BN-HER2 immunotherapy with PD-1 blockade resulted in high LAG-3 expression on CD8 T cells and CD8 T cell infiltration throughout the tumor and co-localization of CD4 and LAG-3 in patches of the tumor." (PMID 26910562, 2016). "Specifically, CD8+ cytotoxic T cells and CD4+ T helper one cells can destroy up to large tumor masses." (PMID 27461275, 2016).
tumor (continued). "The interaction between TIM-3 and CD4 Th1 cells has been studied in pancreatic cancer patients and found to correlate with tumor vascular invasion." (PMID 26981244, 2016). "CD4+ T cell-dependent anti-tumor immunity is the immunological driver behind beneficial clinical responses to cancer." (PMID 27323782, 2016). "The malignant clone of tumor cells has a negative regulatory role in recognizing foreign antigens of CD4+ cells." (PMID 27154067, 2016). "In tumor microenvironments, PD‐1 expression was not only restricted to CD4+ T cells but was also observed from a variety of other immune cells, including macrophages, natural killer (NK) cells, and CD8+ T cells." (PMID 27709793, 2016). "Clinical studies have reported a link between the presence of a tumor and an increase of CD4+CD25+ cells in the blood." (PMID 27036297, 2016). "Specifically, 2×104 CD4+CD25− Tcon cells were used for the host group with high tumor dose and 1×104 CD4+CD25− Tcon cells were used for the host group with low tumor dose." (PMID 27774524, 2016). "We isolated at least 5 high-affinity A2/MART1 TCR clonotypes that recognized A2+ MART1+ tumor cells in a CD8-independent manner when expressed in CD4+ T cells." (PMID 27030642, 2016). "The ΔhtrA mutant, which completely lost its tumor suppressive capacity, induced 1.2% of CD4+ T cells on the 3rd day post infection." (PMID 27835896, 2016). "The helper function of anti-tumor CD4+ T-cells improves the efficacy of anti-tumor CD8+ T-cells; seen early on in studies where transfecting tumor cells with MHC class II genes resulted in increased anti-tumor immune responses." (PMID 25690042, 2015). "In a separate study, treatment with chimeric-NKG2D T cells also increased the number of host CD4+ and CD8+ T cells at the tumor site and increased the number of antigen-specific host CD4+ T cells in the tumor and draining lymph nodes." (PMID 25806106, 2015). "Once activated immune cells kill tumor, dead tumor releases a huge amount of tumor antigen in an immune preferential environment followed by polyclonal antitumor CD4 and CD8 T cells activation, so-called antigen spreading." (PMID 26538233, 2015). "We found that Tregs from both wild type and tumor-bearing mice profoundly suppressed CD4+CD25−T cell proliferation as assayed by incorporation of tritiated thymidine." (PMID 25593198, 2015). "Opposing biological functions, including tumour-promoting versus tumour-suppressive effects, have been reported by several investigators for Treg cells, CD4+ T cells,macrophages and NK cells, according to their distinct functional subsets." (PMID 25970543, 2015). "This was supported by increased infiltration of CD4+ and CD8+ T cells into the tumour microenvironment, in association with decreased tumour growth and increased survival compared to parental HSV." (PMID 26633468, 2015). "After 8 weeks of ethanol administration or regular food, the mice were implanted with the tumor cells and also received one injection of the anti-CD4 antibody." (PMID 26695753, 2015). "Quantification of tumor-infiltrating T cells by flow cytometry showed that the percentages of total T cells, and CD4+ and CD8+ T cells were higher in LRT followed by CTLA-4 blockade in both T1 and T2." (PMID 25980578, 2015). "Some studies concluded that PD-L1 expression is up regulated in solid tumors, where it can provide direct tumor protection and reduce activity of PDCD1 expressing, tumor-infiltrating effector CD4 and CD8 T cells." (PMID 26562534, 2015). "5AZA2-treated tumor cells induced a higher yield of tumor-infiltrating CD4, CD8 T cells, and NK cells and IFNγ production was also elevated in both T-cell compartments." (PMID 25699047, 2015). "We found that most tumor-infiltrating CD4+ T cells were Foxp3+ Tregs (around 70% in E0771 tumors), and there were very few Th17 and Th2 cells in the tumor stroma." (PMID 25760243, 2015).
tumor (continued). "Upon stimulation, naïve CD4+ T cells differentiate into effector cells known as T helper (Th) cells, and the distinct CD4+ T cell subsets have variable impact on tumor growth." (PMID 25689070, 2015). "IL-3 is mostly secreted by activated T-cells and enhances the development of tumor-reactive cytotoxic cells by a CD4-dependent mechanism." (PMID 25776849, 2015). "Many current tumor vaccine trials aim to simultaneously activate tumor antigen-specific CD4+ and CD8+ T cells, expecting a synergistic anti-tumor effect." (PMID 26447332, 2015). "It is well documented that CD4+ T cells play a central role in orchestrating anti-tumor immunity and in priming and maintenance of CD8+ Tcell effector functions." (PMID 26556756, 2015). "In the case of the Foxp3− CD4+ T-cell population, the tumour-infiltrating T-cell population is far more heterogeneous." (PMID 25495686, 2015). "Regarding tumor-specific responses, the percentages of CD4+ T cells, CD8+ T cells, and memory T cells were increase significantly in the TA-loaded-DC vaccination groups compared to the group administered Rv2299c alone." (PMID 26418952, 2015). "Similar functional deficiencies were observed after co-culture with infiltrating CD4+ T cells, including inhibited proliferation and dampened IFNγ and IL-4 production, cytokines that mediate anti-tumor activity." (PMID 25941795, 2015). "Such inhibition is more effective on T cell subsets prevalently involved in anti-tumor immune response (i.e., central and effector memory CD4+ T cells and memory CD8+ T cells)." (PMID 26329660, 2015). "Type I interferon signals are specifically required for the cross presentation of tumor antigen by dendritic cells to both CD4 and CD8 T-cells to allow development of an adaptive immune response." (PMID 26690220, 2015). "Recently we demonstrated the immunogenicity and tumour protection of mice immunised with covalent conjugates of Antp with OVA and synthetic peptides of Antp linked in tandem to OVA CD8, CD4 and CD8/CD4 epitopes." (PMID 26247926, 2015). "In this article, we discuss the role of tumor antigen-specific CD4 T cell responses and how we can target these cells to improve cancer vaccines." (PMID 26350591, 2015). "IL-6 blockade also restores the impaired ability of CD4+ T cells to promote CD8+ T-cell-dependent tumour elimination in aged mice, which requires IFN-γ." (PMID 25850032, 2015). "Extracellular antigens are usually processed and presented via MHC-II by APCs to CD4+ T cells; however, tumor antigens engulfed by APCs need to be presented via MHC-I to activate CTLs, which are the main effector cells against tumor cells." (PMID 26350600, 2015). "Tumor-related immune cells, such as cytotoxic T cells, CD4+ T cells, Treg cells, myeloid-derived suppressor cells (MDSC), and natural killer (NK) cells, have all been reported to be involved in the development of HCC." (PMID 25689070, 2015). "Vaccine-mediated naïve T-cell priming is inhibited due to a minor but distinct population of tumor-reactive CD4+ T cells, generated in the tumor-draining LNs and systemically redistributed." (PMID 25784913, 2015). "One of the most promising pathways for manipulation involves PD-L1, where its up-regulated expression in solid tumors provides direct tumor protection as well as reducing the activity of PDCD1 expressing tumor-infiltrating effector CD4 and CD8 T cells." (PMID 26562534, 2015). "As expected, Foxp3+CD4/CD8 ratios were dramatically increased with the tumor progression in both tumor models." (PMID 25968569, 2015). "It’s reported that in early tumor stages, Th1 cells are the dominant population of CD4+ T cells, perhaps important for immunosurveillance; while in the advanced tumor stages, FoxP3+ Treg and Th17 cells become the dominant populations." (PMID 26587366, 2015). "Higher numbers of administered DCs revert this effect, allowing CD4+ T-cell priming comparable to tumor-free mice." (PMID 25784913, 2015).